AXL (AXL receptor tyrosine kinase)
Diseases named in the same sentence as AXL in open-access papers (continued):
Sharing a sentence is not in itself a finding about the gene and the disease.
tumor (continued). "In tumor tissues, seven gene amplification mutations included CDK4 (Mutation abundance, MA:1.57), AKT2 (MA:1.65), CCND2 (MA:1.63), MDM2 (MA:1.57), NTRK1 (MA:2.38), AXL (MA:1.65), and KRAS (MA:1.63), as well as the AFF3 gene missense (c.1781_1787del insC)." (PMID 37089080, 2023). "MDK/ALK/ALP and GAS/MERTK/AXL interactions between tumor cells and endothelial cells/fibroblasts may be potential therapeutic targets for PTC." (PMID 37733241, 2023). "In addition, the critical role of the KRASG12D-driven reciprocal AXL/IGF1R-AKT signaling axis was validated in regulating tumor cell proliferation and apoptosis." (PMID 37209817, 2023). "AXL plays an essential role in shaping the process of tumor immune tolerance." (PMID 37328828, 2023). "AXL also is expressed by tumor stromal cells, including ECs." (PMID 37469409, 2023). "Although tumor growth rates were different in SNU1196 and HUCCT1 cell monolayers (64 h vs. 8 h), AXL inhibition induced the migration of both tumor cell lines to fill the wounded (scratched) area, demonstrating that AXL plays a critical role in regulating tumor cell migration." (PMID 36980768, 2023). "In this context, the detection of a subset of circulating tumor cells (CTCs) that express AXL (AXL+ CTCs) could be clinically relevant." (PMID 38132919, 2023). "The effect of soluble AXL in tumor-cell invasion was also examined using an invasion chamber assay." (PMID 36980768, 2023). "It is also important to note that in a recent study, miR-34a and miR-34b/c gene silencing decreased apoptosis and cell viability and increased tumor grade as well as inducing the expression of lymph node metastasis-associated genes, including INHBB, AXL, FGFR1, and PDFGRB." (PMID 38116556, 2023). "Additionally, tumor cells upregulate AXL and Gas6 expression in presence of monocyte myeloid-derived suppressor cells (M-MDSCs) and polymorphonuclear myeloid-derived suppressor cells (PMN-MDSCs)." (PMID 37265798, 2023). "Also, a recent study showed that combining AXL-CAR T cells with MWA compared to AXL-CAR T cell therapy alone has better anti-tumor efficacy in NSCLC patient-derived xenografts." (PMID 38017494, 2023). "In addition to the role for VEGF in modulating the tumor microenvironment and immune system, AXL also regulates the anti-tumor immune response." (PMID 38275827, 2023). "Patients with AXL gene alterations were also recruited for another phase I study to determine the safety, tolerability, pharmacokinetics, and anti-tumor effects induced by Mipasetamab Uzoptirine (ADCT-601) alone, or in combination with other anti-cancer drugs (NCT05389462)." (PMID 36980534, 2023). "To mimic and verify whether ligand–induced activated AXL interacts with MIG6 in a tumor microenvironment, we applied GAS6, a ligand for the AXL receptor, to activate AXL in vitro." (PMID 37834326, 2023). "However, in our study, VGFR3 and AXL were significantly decreased in tumour compared with healthy controls." (PMID 36890818, 2023). "Recent studies also suggest that TAM receptors, such as MERTK and AXL may contribute to immunosuppression through cancer intrinsic mechanisms, such as increased PD-L1 expression on tumor cells." (PMID 35572601, 2022). "Moreover, aberrant glycosylation of AXL was reported to mediate tumor cell proliferation, invasion and metastasis." (PMID 35303925, 2022). "Thus, AXL plays multiple roles in tumor progression and metastasis through its modulation of several steps of the metastatic cascade and therapy resistance." (PMID 35158733, 2022). "For example, UZLX-STS84UPS that showed response to EnaV with significant tumor growth delay, tumor regression, and prolonged survival had an AXL IHC-score of only one, while UZLX-STS3DDLPS that responded with only significant tumor growth delay had a score of three." (PMID 35886842, 2022). "Furthermore, since AXL activation is linked to PD-L1 expression on cancer cells, combining PD-L1 and AXL inhibition was able to increase the anti-tumor efficacy in vivo." (PMID 35158733, 2022).
tumor (continued). "AXL inhibitors control the polarization of macrophages to boost tumor immunity." (PMID 36159818, 2022). "In the PyMT BCa model, AXL expressing tumors displayed increased PD-L1 on tumor cells." (PMID 35572601, 2022). "As AXL is known to regulate the inflammatory response of the innate and adaptive immune systems, the mechanism of tumor growth inhibition may be related to these responses." (PMID 35356198, 2022). "We investigated whether AXL expression promotes metformin-induced suppression of tumor growth in vivo using a xenograft mouse model of EAC." (PMID 35936716, 2022). "Another possible tumor-driving pathway with TNS2 includes AXL, IRS-1, and GLUT4." (PMID 35804982, 2022). "These beneficial outcomes were accompanied by higher infiltration of CAR T cells (comb-CAR T cells) in both the peripheral blood on days 42 and 54 and harvested tumours than that in the AXL-CAR T group (mono-CAR T cells), despite the dosage of CAR T cells that was twice higher in the latter group." (PMID 36261437, 2022). "AXL is thus an attractive target for controlling resistance to anti-tumor therapies." (PMID 35356198, 2022). "However, the presence of warfarin following gemcitabine treatment significantly reduced metastatic tumour burden, AXL activation (pAXL) and proliferation (Ki67+) of disseminated cancer cells, but immune cell infiltration remained unchanged by warfarin." (PMID 35022267, 2022). "Forced expression of AXL, but not a kinase-deficient mutant, was sufficient to induce erlotinib resistance in erlotinib-sensitive tumor cells." (PMID 35708914, 2022). "The tumor microenvironment’s immunosuppression and the survival, proliferation, migration, invasion, and metastasis of tumor cells are all significantly influenced by the oncogenic receptor tyrosine kinase AXL." (PMID 36159818, 2022). "Interestingly, gene sets enriched for inflammatory responses, ECM organization, and fibroblast migration were negatively enriched in ROBO3- and AXL-depleted tumor cells." (PMID 35993361, 2022). "AXL inhibition by SKI-G-801 also enhanced the overall survival of C3PQ tumor-bearing mice." (PMID 35356198, 2022). "The AXL inhibitor NSP1034 delayed tumor growth when combined with osimertinib." (PMID 36482474, 2022). "Thus, AXL is an attractive therapeutic target to impair multiple stages of cancer progression by affecting a wide variety of cell types within the tumor." (PMID 35158733, 2022). "The AXL54-x-CD3 is highly specific to AXL expressing tumor cells." (PMID 36551940, 2022). "However, it has been showed that AXL, one of the main targets of cabozantinib, promotes tumor immune evasion and is a candidate factor of resistance to PD‐1 blockade." (PMID 35603906, 2022). "To investigate whether AXL expression provides a clinical advantage in the treatment of tumors with metformin, we used a tumor xenograft mouse model of FLO-1-shCtrl or FLO-1-shAXL cells." (PMID 35936716, 2022). "The Tyro3, AXL, and MerTK (TAM) receptor family regulate tumor-associated macrophages that elicit an immunosuppressive tumor microenvironment, and blockade of TAM receptors via cabozantinib may invigorate antitumor immune activation." (PMID 36969746, 2022). "Consistent with the view that the ROBO3/AXL regulatory network promoted tumor aggressiveness through the IL-6/STAT3 axis, we observed significantly reduced expression of AXL and p-STAT3 in dCas9-ROBO3 tumors, whereas tumors derived from LacZ showed robust expression of AXL and p-STAT3." (PMID 35993361, 2022). "Notably, BGB324 (also known as R428), a small molecule inhibitor of AXL, has exhibited significant inhibitory effects on tumour proliferation and migration in various cell lines, including squamous cell carcinoma, head and neck cancer, and breast cancer cells." (PMID 36203174, 2022). "We observed that administration of AXL-CAR T cells alone moderately suppressed tumour growth, which could be due to the hypofunction of CAR T cells in the immunosuppressive microenvironment." (PMID 36261437, 2022).
tumor (continued). "Four of 13 overlapped markers (MXRA8, CLMP, VCAN and FBLN1) are involved in cell adhesion and tumor metastasis, suggesting that dysfunctions in cell adhesion pathways could lead to anti-PD-1 resistance associated by RIPK1 and AXL." (PMID 36518525, 2022). "Thus, in a cancer context, AXL expression in tumor cells and in stromal cells can contribute to the progression of the disease." (PMID 35158733, 2022). "Of note, AXL inhibition using bemcentinib could only partially restore tumor cell sensitivity to lymphocyte-mediated lysis, suggesting that additional factors mediate immune resistance and evasion of these carcinoma cells." (PMID 35572601, 2022). "The genetic or pharmacological inhibition of AXL could prevent or overcome the acquired resistance to EGFR TKIs and restore sensitivity to erlotinib in tumor models, identifying AXL as a promising therapeutic target." (PMID 35053080, 2022). "In addition, analysis of 89 HPV( +) and 409 HPV(-) primary HNC tumor samples in the TCGA as well as 33 HNC cell lines in Cancer Cell Line Encyclopedia (CCLE) showed a positive correlation between AXL and NRG1 mRNA levels." (PMID 35461210, 2022). "Since free MMAE can also diffuse back out of the cells, EnaV has the potential to cause additional bystander effects by killing surrounding AXL-negative tumor cells." (PMID 35886842, 2022). "Because of AXL’s discriminative expression and its implication in both tumour biology and chemotherapeutic resistance, a therapeutic that targets AXL could be valuable cancer therapy." (PMID 36261437, 2022). "Of note, a direct association between IGF1R and AXL pathways is not reported, but tumor cells expressing low AXL levels exhibit high levels of IGF1R phosphorylation." (PMID 36224313, 2022). "Indeed, KRAS mutated tumor cells induced stromal cells to secrete IGF1 and GAS6 that in turn activated IGF1R and AXL signaling in tumor cells, leading to increased mitochondrial performance, proliferative capacity, and resistance to apoptotic stimuli." (PMID 36324182, 2022). "The over-expression and signaling of the receptor tyrosine kinase AXL by its ligand Gas6 on the surface of several cancer cell lines has been shown to promote their tumor progression, to correlate with their metastatic potential, and can lead to resistance to current cancer therapy." (PMID 36551940, 2022). "Finally, this article discusses the GAS6/AXL signaling pathway in the context of several immune responses such as NK cell activation, apoptosis, and tumor-specific immunity, especially PD-1/PDL-1 signaling." (PMID 34778071, 2021). "Pairwise boxplot also suggested that the AXL mRNA in tumor samples could have a higher expression (P < 0.001)." (PMID 34838035, 2021). "Indeed, blockade of MERTK or AXL using a specific antibody or treatment with sitravatinib or R428 synergized with anti-PD-1 or anti-PD-L1 therapy to enhance anti-tumor immune responses." (PMID 34830794, 2021). "Moreover, other studies have linked AXL/PI3k signaling with increased expression of PD-L1 by tumor cells, and AXL inhibition potentiates PD-1 blockade in ID8 graft models." (PMID 34778071, 2021). "Having shown the existence of AXL-positive cell populations in primary tumors and in tumor-derived cell lines, next, we tested whether these cells had phenotypic and molecular features of Erlotinib-resistant AXL-positive cells." (PMID 34254585, 2021). "Moreover, combined AXL inhibition with PD-1 blockade was shown to mount a potent synergistic antitumor response, leading to tumor eradication in breast, colorectal, and ovarian murine tumor models." (PMID 33922556, 2021). "Therefore, this review focuses on the role of the GAS6/AXL signaling pathway in triggering the immunosuppressive tumor microenvironment as immune evasion." (PMID 34778071, 2021). "Equally important for tumour biology is AXL function in dendritic and NK cells." (PMID 34638349, 2021).
tumor (continued). "We demonstrate that AXL-positive cells are already present as a subpopulation of cancer cells in Erlotinib-naïve tumors and tumor-derived cell lines and that the expression of AXL is regulated through a stochastic mechanism centered on the epigenetic regulation of miR-335." (PMID 34254585, 2021). "Finally, we identify that a combined inhibition of AXL and TGFβ showed a significant anti-tumor activity in vitro and in patient-derived spheroids from primary and secondary CRC tumors." (PMID 33570712, 2021). "We studied the anti-tumor activity of AXL and TGFβ blockade in in vitro models of human CRC." (PMID 33570712, 2021). "Additionally, AXL signaling suppresses immune responses in tumour microenvironment and thereby helps cancer cells to evade immune surveillance." (PMID 34638349, 2021). "The engagement of PtdSer with GAS6 may lead to the activation of AXL signaling in hybrid EMT/MET tumour cells." (PMID 34638349, 2021). "Moreover, AXL expression in tumour cells mediates T cell cytotoxicity resistance, further favouring an immunosuppressive tumour microenvironment." (PMID 33546207, 2021). "Hence, we analyzed the presence of AXL-positive cells in multiple tumor-derived cell lines and correlate their distribution with the mesenchymal status of the cells." (PMID 34254585, 2021). "Tumor cells may induce the expression of AXL and GAS6 in monocytic myeloid-derived suppressor cells (M-MDSCs) and polymorphonuclear myeloid-derived suppressor cells (PMN-MDSCs)." (PMID 34778071, 2021). "In our present study, to our surprise, AXL was highly expressed in TECs, but not in tumor cells, and was negatively associated with overall survival (OS) and disease-free survival (DFS) in HCC patients." (PMID 34123800, 2021). "In support of these speculations, the majority of relapsed tumours were found to have increased AXL and reduced MITF expression, similar to the escapee population observed here." (PMID 33741929, 2021). "There was a positive relationship between CD31 expression and AXL expression in tumor cells (R = 0.600, p < 0.001), which indicates that AXL might promote angiogenesis in the tumors of HCC patients with PVTT." (PMID 34123800, 2021). "We observed an elevated AXL protein expression in PTXR-derived tissues from primary metastatic lung nodules and tumor xenografts compared to parental-derived tumor tissues but AXL gene expression is only markedly increased in primary lung metastasis and metastasized lung tumors in liver and spleen." (PMID 33850249, 2021). "Besides being critically involved in tumor cell survival, proliferation, metastasis, and invasion, AXL also participates in immunotherapy resistance and immunosuppression regulation." (PMID 33922556, 2021). "However, the prognostic role of the combination of these biomarkers and the anti-tumor effect of AXL and TGFβ inhibition in CRC still has to be assessed." (PMID 33570712, 2021). "Upregulated AXL and its interaction with EGFR were associated with resistance to PI3Kα inhibition due to sustained mTOR activation, and addition of AXL inhibitor R428 sensitized tumor cells to PI3Kα." (PMID 34830794, 2021). "We wondered if AXL-positive cells are present in tumors before treatment as well as in tumor-derived cell lines and whether these cells bear phenotypic and molecular similarities to the AXL-positive cells that are generated upon exposure to EGFR TKi." (PMID 34254585, 2021). "However, it must be noted that AXL is a multifunctional protein with roles in promoting cell growth, cell migration, tumor invasion, and dampening inflammatory cytokine production." (PMID 34797899, 2021). "High AXL expression was observed in TECs, but not in the tumor cells of HCC patients with PVTT and this was associated with poor overall survival (OS) and disease-free survival (DFS)." (PMID 34123800, 2021). "In addition, the implication of AXL in epithelial cell plasticity in tumours explains its role in drug resistance and metastasis." (PMID 34638349, 2021).
tumor (continued). "In addition to AXL function in professional phagocytes, AXL expression in tumour cells is yet another factor contributing to immunosuppression." (PMID 34638349, 2021). "It is reported that dysregulation of AXL expression is very common in the resistance of tumor cells to EGFR TKIs, the up-regulation of AXL can be detected after the first generation EGFR TKIs gefitinib, erlotinib 31 and the third generation EGFR TKI Osimertinib 32 acquired resistance." (PMID 34335945, 2021). "Dual treatment with the TGFβ galunisertib and the AXL inhibitor, bemcentinib, significantly reduced colony formation and migration capabilities of tumor cells and displayed a strong anti-tumor activity in 3D spheroid cultures derived from patients with advanced CRC." (PMID 33570712, 2021). "AXL is overexpressed in cells of solid tumours suggesting that GAS6-AXL-DOCK180-ELMO pathway may theoretically enable cancer cells to clear tumour tissues from apoptotic corpses." (PMID 34638349, 2021). "Indeed, AXL was expressed in tumor vessels (87.5%, n = 266), in HCC tumor cells (4.28%, n = 13), and in both HCC tumor cells and TECs (8.22%, n = 25) of total samples." (PMID 34123800, 2021). "AXL regulates tumor invasion through the transcriptional activation of SLUG in HCC." (PMID 34123800, 2021). "In cells of the tumour microenvironment, AXL pathway potentiates immune evasion." (PMID 34638349, 2021). "In terms of immunity, AXL was found to be significantly related to tumor microenvironment, immune checkpoint molecules and immune infiltration by our results, indicating that AXL might play vital roles in immunity." (PMID 34838035, 2021). "We found that AXL-CAR-T cells could effectively kill AXL-positive TNBC cells both in vitro and in vivo, and that C7R could greatly activate AXL-CAR-T cells so as to increase the cytotoxicity of AXL-CAR-T cells towards AXL-positive tumor cells." (PMID 31998790, 2020). "Further investigation identified that the extracellular portion of AXL (sAXL) can be found in serum/plasma from the patients, indicating the level of sAXL could be a surrogate biomarker for the tumor burden in NF1 patients." (PMID 32252313, 2020). "AXL plays a critical role during vascular injury, and its angiogenic role has been widely explored in cancer and AXL inhibition successfully reduces angiogenesis and tumor growth in mouse models." (PMID 32998369, 2020). "Taken together, the data clearly showed that both AXL and c-ABL have an identical clinicopathological association profile and the concurrent expression of these two proteins was significantly associated with EAC patient age, tumor stage, and lymph node status." (PMID 32922529, 2020). "To determine whether the AXL/PEAK1 connection is required for tumor growth and metastasis, we used the PEAK13PA mutant that we demonstrated to be uncoupled from AXL-induced phosphorylation." (PMID 32681075, 2020). "Third, it remains unclear whether VM and AXL expression on CTCs correlates to those in primary tumor tissue." (PMID 31999390, 2020). "Our data, that the silencing of hMENA/hMENAΔv6 in CAFs reduced GAS6 expression and secretion leading to the inhibition of CAF‐induced cancer cell invasiveness, are in agreement with a recent study showing that CAF‐derived GAS6 can activate AXL and promote tumor cell migration." (PMID 32909687, 2020). "Using a mouse subcutaneous xenograft model, we found that AXL-CAR-T cells could mediate elimination of the tumor, and that the expression of C7R in AXL-CAR-T cells could extend their survival time in mice and increase their infiltration and cytokine release." (PMID 31998790, 2020). "In addition, it also inhibited the growth of MET and AXL‐independent SNU719 cells at higher but clinically relevant doses through tumor microenvironment." (PMID 34766112, 2020). "For these studies, the modulation of phosphorylated AXL in the H1299 tumor model was chosen." (PMID 33425754, 2020).